USPL1 (ubiquitin specific peptidase like 1)
Description:
SUMO-specific isopeptidase involved in protein desumoylation. Specifically binds SUMO proteins with a higher affinity for SUMO2 and SUMO3 which it cleaves more efficiently. Also able to process full-length SUMO proteins to their mature forms. Plays a key role in RNA polymerase-II-mediated snRNA transcription in the Cajal bodies. Is a component of complexes that can bind to U snRNA genes.
Synonyms: C13orf22; bA121O19.1; D13S106E
Tractability: Small molecule: a structure with a bound ligand is known. PROTAC: ubiquitination databases record sites on it.
Gene: Protein-coding gene on chromosome 13 (30,617,693 to 30,660,770, forward strand). Ensembl gene ENSG00000132952.
Subcellular location: Nucleus, Cajal body
Gene Ontology:
Molecular function: deSUMOylase activity; protein binding; SUMO binding; ubiquitin binding
Biological process: Cajal body organization; cell population proliferation; protein desumoylation; snRNA transcription
Cellular component: Cajal body; extracellular region
Genetic constraint (gnomAD): Loss-of-function variants: 24 observed, 44.93 expected, observed/expected ratio (o/e) 0.53, 90% interval 0.39 to 0.75. The upper end of that interval is the gene's LOEUF score, 0.75, which puts it in group 3 of 6, group 1 being the genes least tolerant of losing a copy. Missense variants: 1,199 observed, 1,297.5 expected, observed/expected ratio (o/e) 0.92, 90% interval 0.88 to 0.97. Synonymous variants: 446 observed, 472.93 expected, observed/expected ratio (o/e) 0.94, 90% interval 0.87 to 1.02.
Homologues: Orthologues: chimpanzee USPL1 (99% identical), macaque USPL1 (95% identical), pig USPL1 (75% identical), dog USPL1 (73% identical), guinea pig USPL1 (63% identical), mouse Uspl1 (60% identical), rabbit USPL1 (58% identical), rat Uspl1 (57% identical), tropical clawed frog uspl1 (30% identical), zebrafish uspl1 (21% identical).
Diseases named in the same sentence as USPL1 in open-access papers:
USPL1 is named in the same sentence as 8 diseases in open-access papers, as found by Europe PMC text mining. Sharing a sentence is not in itself a finding about the gene and the disease. The quoted sentences say what the papers report.
breast carcinoma (2 papers, 2015 to 2022). "In addition, genetic Uspl1 variants affecting its expression have been linked to breast cancer risk and cancer grade, indicating its importance in breast cancer." (PMID 36313646, 2022). "Many of those hits were supported by literature, whereby some hits were so far overlooked in the context of breast cancer (e.g., Lonp1, Uspl1) or cancer in general (e.g., Psmd13, Tysnd1)." (PMID 36313646, 2022).
gastric cancer (1 paper, 2022). A primary or metastatic malignant neoplasm involving the stomach. "In line with our data, Uspl1 mRNA expression was found to be upregulated in gastric cancer and oral squamous cell carcinoma." (PMID 36313646, 2022).
tumor (2 papers, 2021 to 2022). "The strongest DepMap co-dependent genes for USPL1 across tumor types were members of the Little Elongation Complex (LEC), which is involved in transcription of spliceosomal machinery suggestive of an association between USPL1 and the LEC." (PMID 35737447, 2022). "Further subgroup analyses indicated that SAE1 and UBE2I had differential expressions with different stages, while SENP1, USPL1, SENP2, SENP5, SAE1, UBA2, and UBE2I had differential expressions with different tumor grades." (PMID 34267779, 2021). "Moreover, SENP1, USPL1, SENP2, SENP5, SAE1, UBA2, and UBE2I had differential expressions with different tumor grades." (PMID 34267779, 2021).
USPL1 also shares sentences with these, for which no sentence is quoted: cancer (2 papers); infection (1); lung adenocarcinoma (1); oral squamous cell carcinoma (1); respiratory failure (1).